GATA3 (GATA binding protein 3)
Description:
Transcriptional activator which binds to the enhancer of the T-cell receptor alpha and delta genes. Binds to the consensus sequence 5'-AGATAG-3'. Required for the T-helper 2 (Th2) differentiation process following immune and inflammatory responses. Positively regulates ASB2 expression (By similarity). Coordinates macrophage transcriptional activation and UCP2-dependent metabolic reprogramming in response to IL33. Upon tissue injury, acts downstream of IL33 signaling to drive differentiation of inflammation-resolving alternatively activated macrophages.
Synonyms: HDR; HDRS
Tractability: PROTAC: ubiquitination databases record sites on it.
Safety:
Unwanted effects reported when the protein is acted on. In parentheses: how it was acted on, where the effect was seen, and who reports it.
require glucarpidase treatment (source: ClinPGx)
Gene: Protein-coding gene on chromosome 10 (8,045,315 to 8,075,198, forward strand). Ensembl gene ENSG00000107485.
Subcellular location: Nucleus
Subcellular location (Human Protein Atlas): Nucleoplasm
Pathways (Reactome):
Developmental Biology: Developmental Lineage of Mammary Stem Cells; Differentiation of naive CD4+ T cells to T helper 2 cells (Th2 cells); Formation of the nephric duct
Gene expression (Transcription): RUNX1 regulates transcription of genes involved in differentiation of HSCs
Hemostasis: Factors involved in megakaryocyte development and platelet production
Immune System: Interleukin-4 and Interleukin-13 signaling
Metabolism of proteins: Ub-specific processing proteases
Signal Transduction: Estrogen-dependent gene expression
Gene Ontology:
Molecular function: cis-regulatory region sequence-specific DNA binding; DNA-binding transcription activator activity, RNA polymerase II-specific; DNA-binding transcription factor activity; DNA-binding transcription factor activity, RNA polymerase II-specific; DNA-binding transcription repressor activity, RNA polymerase II-specific; E-box binding; HMG box domain binding; protein binding; RNA polymerase II cis-regulatory region sequence-specific DNA binding; RNA polymerase II-specific DNA-binding transcription factor binding; sequence-specific double-stranded DNA binding; transcription cis-regulatory region binding; DNA binding; histone methyltransferase binding; identical protein binding; interleukin-2 receptor binding; RNA polymerase II transcription regulatory region sequence-specific DNA binding; sequence-specific DNA binding; transcription coactivator binding; zinc ion binding
Biological process: cellular response to interferon-alpha; cellular response to interleukin-4; cellular response to tumor necrosis factor; ear development; kidney development; lymphocyte migration; mesenchymal to epithelial transition; negative regulation of cell cycle; negative regulation of cell motility; negative regulation of DNA-templated transcription; negative regulation of endothelial cell apoptotic process; negative regulation of epithelial to mesenchymal transition; negative regulation of inflammatory response; negative regulation of mammary gland epithelial cell proliferation; positive regulation of DNA-templated transcription; positive regulation of endothelial cell migration; positive regulation of interleukin-13 production; positive regulation of interleukin-5 production; positive regulation of miRNA transcription; positive regulation of phosphatidylinositol 3-kinase/protein kinase B signal transduction; positive regulation of signal transduction; positive regulation of thyroid hormone generation; positive regulation of transcription by RNA polymerase II; positive regulation of transcription regulatory region DNA binding; regulation of cellular response to X-ray; and 50 more
Cellular component: chromatin; nucleoplasm; nucleus
Genetic constraint (gnomAD): Loss-of-function variants: 6 observed, 31.5 expected, observed/expected ratio (o/e) 0.19, 90% interval 0.1 to 0.38. The upper end of that interval is the gene's LOEUF score, 0.38, which puts it in group 1 of 6, group 1 being the genes least tolerant of losing a copy. Missense variants: 514 observed, 603.34 expected, observed/expected ratio (o/e) 0.85, 90% interval 0.79 to 0.92. Synonymous variants: 326 observed, 272.45 expected, observed/expected ratio (o/e) 1.2, 90% interval 1.09 to 1.31.
Gene-disease validity (ClinGen):
ClinGen rates the evidence that GATA3 causes each of these diseases.
hypoparathyroidism-deafness-renal disease syndrome (autosomal dominant): Definitive. The HDR syndrome is an inherited condition consisting of hypoparathyroidism, sensorineural deafness and renal disease.
Cancer hallmarks: proliferative signalling (promotes); suppression of growth (promotes); escaping immune response to cancer (suppresses); invasion and metastasis (suppresses); escaping programmed cell death (promotes); genome instability and mutations (suppresses); tumour promoting inflammation (promotes); angiogenesis (promotes); change of cellular energetics (promotes); angiogenesis (suppresses)
Homologues: Orthologues: chimpanzee GATA3 (99% identical), macaque GATA3 (99% identical), rabbit GATA3 (98% identical), guinea pig GATA3 (97% identical), mouse Gata3 (96% identical), pig GATA3 (96% identical), rat Gata3 (96% identical), tropical clawed frog gata3 (80% identical), zebrafish gata3 (80% identical), dog GATA3 (63% identical), Drosophila melanogaster srp (32% identical), Drosophila melanogaster GATAd (26% identical), and 2 more. Paralogues in human: GATA2 (66% identical), GATA6 (35% identical), GATA1 (35% identical), GATA4 (32% identical), GATA5 (30% identical), TRPS1 (23% identical), ZGLP1 (9% identical).
Diseases named in the same sentence as GATA3 in open-access papers:
GATA3 is named in the same sentence as 486 diseases in open-access papers, as found by Europe PMC text mining. Sharing a sentence is not in itself a finding about the gene and the disease. The quoted sentences say what the papers report.
breast carcinoma (649 papers, 2006 to 2026). "Low levels of GATA3 expression have been associated with tumour progression and poor patient prognosis in breast cancer." (PMID 40585280, 2025). "Accordingly, loss of GATA3 expression has been reported to be associated with basal-like breast cancer aggressiveness, HER2 overexpression, oestrogen and progesterone receptor negativity, and reduced survival." (PMID 40585280, 2025). "GATA3 mutations are frequent in breast cancer, with an estimated prevalence of 10–18% in HR + MBC; the majority are loss-of-function mutations and are associated with poor response to endocrine therapy (ET) and poor survival, as described in our previous work." (PMID 40439821, 2025). "Several studies have reported frequent somatic mutations of GATA3 up to 18% in breast cancer, predominantly in the ER-positive molecular subtypes." (PMID 40585280, 2025). "GATA3 positivity, which is more commonly associated with breast cancer, has only been described rarely in EMPC." (PMID 39897239, 2025). "In all cohorts, low GATA3 protein and GATA3 mRNA expression associated with overall reduced breast cancer‐specific survival (p ≤ 0.001)." (PMID 41024411, 2025). "Previous studies have shown that high GATA3 expression is commonly observed in Luminal-type breast cancer and is associated with favorable biological behavior." (PMID 40881878, 2025). "Accruing knowledge on the nature of GATA3 gene mutations in breast cancer offers hope for a new arsenal of targeted therapies." (PMID 40439821, 2025). "In breast cancer (BC), the transcription factor GATA3 is linked to estrogen receptor (ER) alpha biology, and its loss is associated with aggressive tumor features." (PMID 41024411, 2025). "GATA3 is also a key transcription factor, whose functional loss is associated with tumor progression in breast cancer." (PMID 41187747, 2025). "GATA3 mutations are frequently identified in small luminal breast cancers with homogeneous enhancing patterns, indicative of a favorable prognosis." (PMID 40002579, 2025). "GATA3 protein, as a transcription factor associated with mammary epithelial differentiation, plays a crucial role in the development and progression of breast cancer." (PMID 40881878, 2025). "We found that the gene GATA3 was most frequently targeted by loss-of-function mutations in at least 8.5% of breast cancers." (PMID 40585280, 2025). "GATA3 mutations were associated with smaller tumor size and uniform textural features, reflecting the radiologic characteristics of luminal breast cancer." (PMID 40002579, 2025). "Genomic sequencing in patients from the Young Women's Breast Cancer Study identified higher rates of GATA3 and ARID1A mutations in women < 35 with luminal A cancer compared to those > 45 (43% vs. 12% and 18% vs. 2%, respectively)." (PMID 39470669, 2025). "In human beings, germline mutations of GATA3 are associated with congenital hypoparathyroidism-deafness-renal disease (HDR) syndrome, and somatic mutations of GATA3 have been detected in ~ 15% of breast cancers." (PMID 38627785, 2024). "The AR-GATA3 interaction was further validated by co-immunoprecipitation (co-IP) assays in which pull down of AR was associated with detection of GATA3 in all four breast cancer cell lines upon treatment with DHT." (PMID 38317241, 2024). "In contrast, higher TRPS1 expression has been associated with better breast cancer patient outcomes, though its expression is highly correlated with ER and GATA3, both favorable prognostic indicators." (PMID 38377146, 2024). "Most of these high-frequent mutations are involved in breast cancer, strongly suggesting that they are closely associated with the phase separation of GATA3." (PMID 38531854, 2024).
breast carcinoma (continued). "Higher GATA3 expression has been reported to be associated with good prognostic criteria in urothelial cancer, such as a lower tumor grade and stage, and in breast cancer, with better tumor differentiation and suppressed metastasis." (PMID 38668712, 2024). "GATA3 transcription factor is expressed in breast ductal cells and crucial for breast development but, while there are many reports of GATA3 mutations in breast cancer (including triple negative tumours), their functional effects are unclear." (PMID 38304083, 2024). "Dysregulation of GATA3 is implicated in several diseases, such as breast cancer (BC), hematological malignancies like T-cell lymphomas, autoimmune diseases, and neurodegenerative disorders." (PMID 39768217, 2024). "The identification of GATA3 as a sensitive diagnostic marker for various cancers, including breast cancer and urothelial carcinoma, enhances the accuracy of disease diagnosis and prognosis." (PMID 39768217, 2024). "Loss of GATA3 expression in breast cancer has been linked to poor prognosis with a higher tumor T stage, HER2 overexpression, estrogen and progesterone receptor negativity, and reduced survival." (PMID 38668712, 2024). "GATA3 is expressed in some breast cancers and functions as a coregulator of ESR1 (encoding ERα) gene transcription." (PMID 39336822, 2024). "Nonetheless, three genes (CNTNAP2, EHF, KDM4B) were significantly upregulated by DHT in all four models of breast cancer and displayed enrichment of AR, GATA3, and H3K27ac ChIP-seq signals at associated genomic loci." (PMID 38317241, 2024). "Somatic mutations in CDH1 are found in around 50% of lobular breast cancers, while GATA3 mutations occur in approximately 10% of breast cancers." (PMID 39329702, 2024). "In conclusion, we have revealed a novel interaction between AR and GATA3 transcription factors in breast cancer cells that was functionally linked to promotion of a more differentiated phenotype." (PMID 38317241, 2024). "Knockdown of GATA3 in human T47D (GATA3 WT) breast cancer cells or haploid loss of Gata3 by heterozygous germline deletion of Gata3 gene in mouse mammary tumor cells impaired DNA damage response in vitro." (PMID 38627785, 2024). "Of particular interest were three DNA-binding factors associated with AR on chromatin in all breast cancer contexts: GATA3, JUNB, and ERF." (PMID 38317241, 2024). "We analyzed genomic DNA isolated from tumors and observed that the remaining wild-type Gata3 allele was retained in all three p18−/−;Gata3+/− mammary tumors tested." (PMID 38627785, 2024). "Taking advantage of the luminal type mammary tumor model system we established, we directly test if Gata3 deficiency impairs DNA damage repair in luminal tumor cells in vivo." (PMID 38627785, 2024). "Reconstitution of Gata3 in Brca1-deficient mammary tumor cells restores the HR efficiency of Brca1-deficient cells and improves DNA damage repair in mammary tumorigenesis." (PMID 38627785, 2024). "We ectopically overexpressed Gata3 in Brca1-deficient mammary tumor cells and then treat them with OLA." (PMID 38627785, 2024). "So, because there are few studies on this topic, future studies should be performed on the expression of GATA-3 in different types of breast cancer as a diagnostic marker for lymphovascular invasion, lymph node metastasis, or other tumor parameters." (PMID 37383162, 2023). "In a study using aggressive breast cancer cell lines in mice susceptible to lung metastasis, an increased expression of GATA-3 resulted in reduced tumor growth and a lower rate of lung metastasis." (PMID 37483298, 2023). "The use of MR enabled us to explore the causality between GATA3 and breast cancer incidence and prognosis." (PMID 37900131, 2023).
breast carcinoma (continued). "GATA3 expression is correlated to estrogen receptor alpha expression and better prognosis and is frequently mutated in breast cancer." (PMID 37454130, 2023). "GATA3 is a transcriptional factor critical for breast development and is associated with luminal transcription in breast cancer." (PMID 37454130, 2023). "There is a causal relationship between downregulation of the GATA3 gene and breast cancer mortality (IVW: p<0.001, WM: p<0.001, simple mode: p=0.03, and weighted model: p=0.02)." (PMID 37900131, 2023). "This gene is mutated in approximately 10–15% of breast cancer cases, suggesting these are driver mutations, and during progression to metastatic breast cancer, GATA3 expression decreases." (PMID 36949070, 2023). "GATA-3 has been reported as a sensitive and specific marker for diagnosing human breast carcinomas, and high expression of this factor is associated with favorable prognostic outcomes." (PMID 37483298, 2023). "An example that illustrates the importance of this is the identification of several breast cancer samples that have splice-associated variants within GATA3 by RegTools." (PMID 36949070, 2023). "The goal of this study was to characterize and evaluate the expression of GATA3 and mammaglobin breast tumors from African American women and determine their association with clinicopathological outcomes including breast cancer subtypes." (PMID 36747860, 2023). "Of the 294 oncogenic TFs, the androgen and estrogen receptors, the BRCA1 and BRCA2 genes, MYC and GATA3 stand out for their association with breast cancer subtypes." (PMID 37564937, 2023). "Together, these data provide the first genetic evidence indicating that loss of function of GATA3 in mammary tumor cells activates FOSL1 to promote mesenchymal traits and CSC function, while concurrently repressing FOS to lose epithelial features." (PMID 37353480, 2023). "We screened and characterized ten tumor cell lines from ten individual p18mt;Gata3+/− primary mammary tumors and established a Gata3 deficient basal-like mammary tumor model system." (PMID 37353480, 2023). "The loss of the GATA3 function coincides with the loss of differentiation and induces basal-like mammary tumors." (PMID 37592347, 2023). "We previously demonstrated that deficiency of Gata3 converts luminal-type mammary tumor cells into basal-like tumor cells with EMT activation." (PMID 37353480, 2023). "The high expression of GATA-3 was associated with a higher survival rate, and can be considered an independent prognostic factor in mammary neoplasms of female dogs." (PMID 37483298, 2023). "Low expression of GATA3 is associated with basal-like features and poor prognosis in breast cancers." (PMID 37592347, 2023). "Consistently, reconstitution of Gata3 in Gata3- or Brca1-deficient human and mouse mammary tumor cells restores the expression of c-Fos and suppresses Fra1 in inhibiting EMT, motility, invasion, and tumorigenesis." (PMID 37353480, 2023). "Together, these findings are in line with our discovery in mice that loss of Gata3 activates Fra1, promoting mammary tumor metastasis." (PMID 37353480, 2023). "We have also shown that haploid loss of Gata3 in p18 deficient mice, i.e., p18mt mice including p18−/− and p18+/− mice, results in metastatic basal-like mammary tumors with EMT features." (PMID 37353480, 2023). "More importantly, the frequency of somatic mutations in GATA3 was even higher in the metastatic breast cancer cohort." (PMID 35154280, 2022).